TMPRSS2 (transmembrane serine protease 2)
Diseases named in the same sentence as TMPRSS2 in open-access papers (continued):
Sharing a sentence is not in itself a finding about the gene and the disease.
prostate carcinoma (continued). "About 50% of prostate cancers carry the gene fusion linking the androgen-regulated serine protease TMPRSS2 with the ETS-transcription factor ERG, resulting in the overexpression of ERG." (PMID 31452838, 2019). "It is important to note that the TMPRSS2-ERG fusion is correlated with aggressive prostate cancer and poor prognosis." (PMID 31366128, 2019). "Lindquist and coworkers have analyzed the genomes of 24 AAM with aggressive prostate cancer with Gleason grades ≥7 and confirmed in these patients a low prevalence of TMPRSS2-ERG fusions (20%) and of PTEN deletions (8%)." (PMID 31366128, 2019). "Here, we evaluate the TMPRSS2-ERG fusion gene in prostate cancer tissue, as representative of a translocation-positive epithelial tumor, for a putative application as a noninvasive ctDNA biomarker." (PMID 31915468, 2019). "In a recent whole genome sequencing study, the TMPRSS2-ERG fusion was identified as an early event in the development of prostate cancer." (PMID 31275657, 2019). "About 50% of prostate cancers carry gene fusions linking the androgen-regulated TMPRSS2 with the transcription factor ERG." (PMID 30823906, 2019). "Prostate cancer (PCa) tumors harboring translocations of ETS family genes with the androgen responsive TMPRSS2 gene (ETS+ tumors) provide a robust biomarker for detecting PCa in approximately 70% of patients." (PMID 30367117, 2019). "The presence of multiple fusion transcript isoforms was most notable in the prostate cancer samples, where 10 out of 11 (91%) TMPRSS2-ERG positive samples expressed two or more alternative isoforms." (PMID 30918253, 2019). "TMPRSS2:ERG fusions occur in about 50% of prostate cancers and result in a permanent expression of the transcription factor ERG." (PMID 31606028, 2019). "In one study, TMPRSS2-ERG gene fusions were highly associated with a Gleason score of ≥7 and prostate cancer-related death." (PMID 31013716, 2019). "Intra-chromosomal translocation of the transmembrane protease serine 2 (TMPRSS2) gene to the ETS family member ERG is the most prevalent fusion in prostate cancer and the fusion gene is expressed in the VCaP cell line." (PMID 30664691, 2019). "Association of the long PDE4D5, PDE4D7, and PDE4D9 transcript scores to prostate cancer patient outcome, after primary intervention, varies in opposite directions depending on the TMPRSS2-ERG genomic fusion background of the tumour." (PMID 31275657, 2019). "TMPRSS2 is an androgen-regulated gene that is overexpressed in prostate cancer tissue and is specifically involved in cancer cell invasion and metastasis." (PMID 31405024, 2019). "A recent study showed that NOTCH factors are direct transcriptional targets of ERG; inhibition of ERG in TMPRSS2-ERG-positive prostate cancer cells and decreased NOTCH1 and NOTCH2 levels." (PMID 31366128, 2019). "A pertinent example for prostate cancer is the TMPRSS2-ERG gene fusion that occurs in ~50–80% of all prostate cancer." (PMID 30679435, 2019). "High-level nuclear ELAC2 staining was associated with TMPRSS2:ERG rearrangement and ERG expression in prostate cancers (p< 0.0001 each)." (PMID 31452838, 2019). "While the biological function of the NIPBL-ERG fusion at present is not known, given the lack of mechanistic studies, our findings suggest that the fusion exerts its function in an analogous manner to TMPRSS2-ERG in prostate cancer." (PMID 31906059, 2019). "For example, it fuses with TMPRSS2 in most prostate cancers, with EWS in Ewing’s sarcoma, and with FUS in AML." (PMID 30736820, 2019). "Common genetic alterations in prostate cancer include HPCI mutation, losses or down-regulation of the tumor suppressor protein NKX3.1, loss or mutation of PTEN, TMPRSS2-AR or ERG1-AR gene fusion, and AR upregulation." (PMID 31088536, 2019). "Other studies have attempted to define peculiar biologic properties of TMPRSS2-ERG-positive prostate cancers." (PMID 31366128, 2019).
prostate carcinoma (continued). "The TMPRSS2:ERG gene fusion occurs in 40–60% of prostate cancers, and results in deregulation of more than 1,600 genes." (PMID 30899444, 2019). "SNW1 expression was strongly linked to TMPRSS2:ERG rearrangement and ERG expression in our set of prostate cancers." (PMID 31043167, 2019). "Exosomes from urine possess mRNA-encoding protein prostate cancer-associated 3 (PCA3) and the transmembrane protease serine 2 (TMPRSS2)–erythroblast transformation-specific (ETS)-related gene (ERG) fusion product, an entity over-expressed in prostate cancer." (PMID 30699987, 2019). "AR transactivation induces the high expression of androgen-regulated genes, including transmembrane protease serine 2 (TMPRSS2) and long noncoding RNA prostate cancer-associated transcript 38 (PRCAT38)." (PMID 31405024, 2019). "We also aimed to identify markers of the most common molecular subtype of prostate cancer carrying a fusion transcript TMPRSS2-ERG." (PMID 31447885, 2019). "A study reported that the androgen-driven TMPRSS2-ERG fusion was associated with deletion at chromosome 3p14, which is specific to prostate cancer." (PMID 31306099, 2019). "Approximately 50% of prostate cancers carry a chromosomal translocation resulting in generation of the TMPRSS2-ERG fusion gene, which is unique to the tumor cells of each individual patient because of variability in the fusion breakpoint sites." (PMID 31915468, 2019). "NCI-H660 is a prostate cancer cell line where two fusion genes (TMPRSS2-ERG and EEF2-SLC25A42) have been verified to play important roles in tumorigenesis." (PMID 31610622, 2019). "The fraction of prostate cancer samples harboring a TMPRSS2-ERG fusion transcript found in this study was in concordance with previously published results." (PMID 31537872, 2019). "As mentioned in the section on genetic abnormalities, the fusion of the AR-regulated TMPRSS2 gene with ERG is a very frequent event during early stages of prostate cancer tumorigenesis." (PMID 31366128, 2019). "The TMPRSS2-EERG fusion protein represents an attractive therapeutic target since it is a key oncogenic driver for some prostate cancers sensitive and resistant to androgen deprivation." (PMID 31366128, 2019). "LncRNA PRCAT38 is specifically overexpressed in prostate cancer, and its expression is positively correlated with TMPRSS2 expression within tumor samples." (PMID 31405024, 2019). "Of importance, the TMPRSS2-ERG fusion protein has been shown to impinge upon several oncogenic pathways relevant to prostate cancer etiology." (PMID 29455671, 2018). "The protein is overexpressed in prostate cancer when the androgen-induced TMPRSS2 (transmembrane serine protease 2) gene fuses to the ERG gene." (PMID 30280090, 2018). "For example, the TMPRSS2-ERG fusion in prostate cancer has also been reported to directly regulate cell migration genes." (PMID 30089255, 2018). "In prostate cancer cells harboring the TMPRSS2–ERG fusion, ERG expression is known to be highly induced by testosterone." (PMID 30291252, 2018). "In the clinical context, reports identified a statistically significant association between TMPRSS2-ERG fusion and prostate cancer specific death." (PMID 29455671, 2018). "Several studies demonstrated that ERG is highly and consistently expressed in many prostate cancer patients because of gene fusion with TMPRSS2, an androgen-dependent gene." (PMID 30237984, 2018). "ERG is a member of the Erythroblast Transformation-Specific (ETS) gene family and is commonly fused in prostate cancer to the TMPRSS2 gene (Transmembrane Protease, Serine 2)." (PMID 30300367, 2018). "Previous observations had prostate cancer divided in distinct molecular subgroups defined by TMPRSS2:ERG fusion and various genomic deletions." (PMID 29304771, 2018). "In the present study, we found that CITED2 was highly expressed in metastatic prostate cancer because of TMPRSS2–ERG gene fusion, which promoted metastasis by activating NCL at the post-translational level." (PMID 30291252, 2018).
prostate carcinoma (continued). "The TMPRSS2-ERG fusion increases bone tropism of prostatic cancers and promotes their metastases in bone." (PMID 29581876, 2018). "Clonal proliferation of NED from an existing prostate cancer is indicated by the prostate cancer specific gene rearrangement TMPRSS2-ERG in NED prostate cancer cases, that most commonly appears following hormonal therapy of hormone sensitive prostate cancer." (PMID 29562686, 2018). "The TMPRSS2:ERG gene fusion is the most prevalent early driver gene activation in prostate cancers of European ancestry, while the fusion frequency is much lower in Africans and Asians." (PMID 30150711, 2018). "In prostate cancer are after the TMPRSS2: ERG fusion, chromosomal deletions the most frequent type of genomic aberration." (PMID 29304771, 2018). "ERG and CITED2 overexpression in the TMPRSS2–ERG gene fusion samples further support the ERG-driven overexpression of CITED2 in prostate cancer cells." (PMID 30291252, 2018). "It was shown that TMPRSS2 mediates androgen-induced prostate cancer cell invasion, tumor growth, and metastasis by stimulating a proteolytic cascade." (PMID 29643838, 2018). "Collectively, these results put the TMPRSS2-ERG fusion at the center of a web of mechanisms responsible for the prostate cancer progression." (PMID 29671777, 2018). "Earlier studies had provided evidence for distinct molecular subgroups of prostate cancer defined by TMPRSS2:ERG fusion and several genomic deletions." (PMID 29855276, 2018). "In prostate cancer, TMPRSS2‐ERG was the most prevalent somatic mutation and appeared to be an early event in the progression of prostate cancer." (PMID 29383875, 2018). "In the patho-physiological context of prostate cancer, TMPRSS2-ERG fusion protein is presumably functioning in the presence of the wild type, untranslocated ERG protein." (PMID 29455671, 2018). "TMPRSS2 was found to be induced by androgen exposure to prostate cancer cells by microarray containing 1,500 cDNAs." (PMID 29643838, 2018). "Because TMPRSS2:ERG fusion is the predominant genetic marker in prostate cancer we analyzed its relation to PSCA expression." (PMID 29855276, 2018). "Among TMPRSS2-ERG translocation positive samples, a characteristic mutation in prostate cancers, fatty acid oxidation related metabolites were significantly increased, namely cerebronic acid, 2-hydroxybehenic acid, and tricosanoic acid." (PMID 29562686, 2018). "TMPRSS2-ERG is a high-frequency fusion gene expressed in prostate cancer and plays a vital role in carcinogenesis." (PMID 30459527, 2018). "A total of 76 relevant articles, published from 2015 to 2017, were obtained from PubMed, Web of Science, EMBASE, Scopus, the Cochrane Library, and CNKI databases to investigate the predictive significance of TMPRSS2-ERG fusion in prostate cancer." (PMID 30459527, 2018). "Since TMPRSS2-ERG fusion is a dominant molecular subtype in prostate cancer in European descents, it provides opportunities for targeted cancer therapy." (PMID 30150711, 2018). "In the specific case of the prostate cancer-specific TMPRSS2-ERG aberrant transcription factor, we have demonstrated that the chimera was able to phosphorylate the IGF1R tyrosine kinase domain and downstream target Akt." (PMID 29455671, 2018). "Genetic rearrangements occurring early in prostate cancer development place ERG oncogene expression under the control of the androgen-regulated TMPRSS2 promoter to hijack cell behaviour." (PMID 28382513, 2017). "We have also found that KANSARL and TMPRSS2-ERG are the two most highly-expressed fusion genes in the VPD prostate cancer dataset." (PMID 28881586, 2017). "Chromosomal deletions represent the most frequent genomic changes in prostate cancer next to TMPRSS2:ERG fusion." (PMID 28747165, 2017).
prostate carcinoma (continued). "Since, over half of the prostate cancer patients harbor TMPRSS2-ERG fusions, understanding the mechanistic role of ERG in mediating oncogenic transformation of prostate epithelium would facilitate better therapeutic strategies." (PMID 28439080, 2017). "One possible limitation of our study is the heterogeneity of TMPRSS2:ERG expression in prostate cancer patient tumors." (PMID 28591703, 2017). "ERG is not normally transcriptionally controlled by androgens, but gene fusions can place ERG under transcriptional control by the androgen-regulated TMPRSS2 gene on the transition between prostatic epithelial neoplasia to prostate carcinoma." (PMID 28382513, 2017). "One confounding factor is that many prostate cancers express a TMPRSS2:ERG fusion gene whose expression is increased both by androgens and by vitamin D receptor (VDR) activation." (PMID 28591703, 2017). "About half of human prostate cancers contain a chromosomal rearrangement between the TMPRSS2 promoter and the coding region of an ETS transcription factor forming a TMPRSS2:ETS fusion gene." (PMID 28591703, 2017). "High-level GGH staining was linked to TMPRSS2:ERG rearrangement and ERG positivity in prostate cancers." (PMID 28146062, 2017). "This is different from other well-established fusions such as BCR-ABL in chronic myelogenous leukemia, TMPRSS2-ERG in prostate cancer, or EWS-FLI1 in Ewing’s sarcoma with junctional variability." (PMID 28978917, 2017). "Transmembrane protease serine 2 (TMPRSS2)-ERG fusion gene is one of the most common genomic alterations identified in about 50% of prostate cancer (urine or tissue)." (PMID 28061466, 2017). "About 50% of prostate cancers carry a gene fusion involving the androgen-regulated serine protease TMPRSS2 and the ETS-transcription factor ERG." (PMID 28146062, 2017). "First, AR can increase spatial association of the transmembrane protease, serine 2 (TMPRSS2) gene and ETS-related gene (ERG) and mediate TMPRSS2-ERG gene fusion, which is a clinical marker of prostate cancer." (PMID 29149895, 2017). "Our study is the first to explore VDR action in prostate cancer using next generation RNA sequencing of the TMPRSS2:ERG positive VCaP cell line." (PMID 28591703, 2017). "The second argument depends on the prevalence of TMPRSS2-ERG gene fusion in prostate cancer which has been reported to range from 40% to 70%, depending on the clinical cohorts investigated." (PMID 28978184, 2017). "More than half of all prostate cancers carry this gene fusion which links the androgen-regulated TMPRSS2 gene with the transcription factor ERG resulting in an androgen-dependent overexpression of the ERG transcription factor." (PMID 28415558, 2017). "Significantly, the 3Mb deletion between ERG and TMPRSS2 on Ch21 was indicative of the TMPRSS2-ERG fusion product, a major molecular hallmark of prostate cancer." (PMID 29145505, 2017). "To illustrate how INTEGRATE-Vis works we focused on a prostate cancer patient harboring the most prevalent gene fusion, TMPRSS2-ERG, that results in the marked increase in the expression of the oncogenic transcription factor ERG." (PMID 29259323, 2017). "We then evaluated the effect of TMPRSS2-ERG on the migration behavior of PC3M-luc prostate cancer cells." (PMID 28055969, 2017). "The first group consists of TMPRSS2-ERG, which was detected in three prostate cancer patients (i.e., TMPRSS2-ERG group)." (PMID 29181411, 2017). "In this regard, there are quite a few precedents, such as prostatic secretory protein-94, PSA, and TMPRSS2, all of which are products of androgen-regulated genes and enhance the progression of prostate cancer." (PMID 28212551, 2017). "The TMPRSS2-ERG gene fusion is the most common gene rearrangement in prostate cancer, with a reported prevalence of 15-78%." (PMID 27276682, 2016).
prostate carcinoma (continued). "As an example of differential distributions of genetic events based on ethnicity, TMPRSS2:ETS gene fusions are found in approximately 50% of prostate cancers in the US, but only 10% of prostate cancers in China." (PMID 27551333, 2016). "Fusion between TMPRSS2 and ERG, placing ERG under the control of the TMPRSS2 promoter, is the most frequent genetic alteration in prostate cancer, present in 40–50% of cases." (PMID 27536883, 2016). "The potential role of ERG as a cancer driver and the high incidence of the TMPRSS2-ERG gene fusion in prostate cancer have catapulted this protein into the forefront of new targets for therapeutic intervention." (PMID 27626314, 2016). "Analysis of prostate cancer samples also showed that miR-221 is down-regulated in patients with TMPRSS2-ERG gene fusion-positive tumours compared to ERG fusion negative samples." (PMID 27208692, 2016). "Tumor SC_9009 expressed a fusion transcript involving the 5′ exons of TMPRSS2 and 3′ exons of ERG, consistent with the commonly observed TMPRSS2-ETS family rearrangements that occur in 40– 60% of prostate cancers." (PMID 27167109, 2016). "In the pathophysiological context of prostate cancer, TMPRSS2-ERG fusion proteins are presumably functioning in the presence of the wild type, untranslocated ERG protein." (PMID 27285981, 2016). "More than 50% of all prostate cancers harbour a chromosomal translocation that results in the fusion of the androgen receptor-regulated gene promoter of transmembrane protease serine (TMPRSS)-2 and ERG." (PMID 27208692, 2016). "The TMPRSS2-ERG fusion occurs in approximately 50% of prostate cancer (PCa), resulting in expression of the oncogenic ERG in the prostate." (PMID 27191272, 2016). "Thirdly, the TMPRSS2/ERG fusion prevalence is significantly different in prostate cancers from different ethnic groups." (PMID 27191272, 2016). "The identification of TMPRSS2-ERG as an important player in prostate cancer etiology had a major impact in basic and translational oncology." (PMID 27285981, 2016). "The most common fusion event (TMPRSS2 exon 1 with ERG exon 4) has been reported as having an incidence between 20%-80% in prostate cancer." (PMID 27144529, 2016). "Here, we constructed a heterogeneity tissue microarray (TMA) comprising samples from 10 different tumor areas of 189 prostate cancers each in order to study the sequence of two frequent molecular alterations, i.e. 6q15 deletion and TMPRSS2:ERG fusion." (PMID 26684029, 2016). "Because basal epithelial cells are lost during prostate cancer development, it is possible that TMPRSS2/ERG-dependent prostate tumors retain more basal cells, resulting in high levels of miR-205 in the tumors." (PMID 27191272, 2016). "We demonstrated that TRIM25 knockdown results in increased ERG stability in TMPRSS2-ERG expressing prostate cancer cells." (PMID 27626314, 2016). "The most common gene rearrangement in prostate cancer is the TMPRSS2-ERG fusion, which results in aberrant expression of the transcription factor ERG." (PMID 27285981, 2016). "The TMPRSS2:ERG gene fusion is common in androgen receptor (AR) positive prostate cancers, yet its function remains poorly understood." (PMID 27183006, 2016). "Probing CRLs in prostate cancer cells revealed a remarkable plasticity of cells with TMPRSS2-ERG translocation." (PMID 27906189, 2016). "The TMPRSS2:ERG gene fusion is one of a series of highly promising prostate cancer (PCa) biomarker alternatives to the controversial serum PSA." (PMID 27470540, 2016). "Our data revealed that MAP3K7 deletion is often heterogeneous in prostate cancer and prevents TMPRSS2:ERG fusion, while TMPRSS2:ERG fusion allows MAP3K7 deletion." (PMID 26684029, 2016). "The present study identifies the IGF1R gene as a novel downstream target for the TMPRSS2-ERG fusion protein in prostate cancer." (PMID 27285981, 2016).